MDH1 (malate dehydrogenase 1)
Diseases named in the same sentence as MDH1 in open-access papers (continued):
Sharing a sentence is not in itself a finding about the gene and the disease.
prion disease (3 papers, 2016 to 2023). A transmissible disease that is caused by a protein that is able to induce abnormal folding of normal cellular proteins, leading to characteristic spongiform brain changes, which are associated with neuronal loss without an inflammatory response. "To study the influence of the PRNP codon 129 MV polymorphism on MDH1-levels in CSF, we stratified our genetic prion disease cohort according to the PRNP codon 129 genotype in gCJD (E200K MM and MV, V210I MM and MV, as well as FFI-D178N MM and MV)." (PMID 31795176, 2019). "In our study, we measured the MDH1 levels in CSF in different types of genetic prion diseases by using a commercial MDH-ELISA kit." (PMID 31795176, 2019). "These interesting observations encouraged us to investigate a potential regulation of MDH1 levels in CSF of genetic prion disease patients in comparison to a neurodegenerative control cohort." (PMID 31795176, 2019). "Our data indicate an enhancement of MDH1 amount as a consequence of rapid neurodegeneration in CSF of genetic prion disease patients compared to controls." (PMID 31795176, 2019). "The analysis of MDH1 levels revealed a significant increase in genetic prion disease patients in comparison to a control group (p < 0.001 ***)." (PMID 31795176, 2019). "The comparative analysis of different genetic prion disease groups indicated higher MDH1 levels in gCJD (E200K and V210I) than in FFI cases (p < 0.001)." (PMID 31795176, 2019). "These promising observations encouraged us to determine the levels of MDH1 in cerebrospinal fluid (CSF) of different types of genetic prion disease patients (gCJD (E200K, V210I), GSS, and FFI)." (PMID 31795176, 2019). "Immunohistochemical staining of cytosolic MDH1 was performed in the frontal cortex region of sCJD (MM1) patients in comparison to non-prion disease controls." (PMID 27852982, 2016). "Besides RT-QuIC, two other biomarkers can be considered specific for prion diseases: malate dehydrogenase 1 with a sensitivity and specificity of over 90% in patients with sCJD and PMCA with an almost 100% specificity and sensitivity to diagnose vCJD." (PMID 37854584, 2023). "MDH1 levels should be determined in a larger patient cohort, which might be challenging due to the rareness of genetic prion disease cases worldwide." (PMID 31795176, 2019). "Moreover, we were also interested in comparing MDH1 levels with different genetic prion disease groups, such a gCJD E200K, V210I, FFI, and GSS." (PMID 31795176, 2019). "At first, we investigated the levels of MDH1 by ELISA (indicated as million units per mL (mU/mL)) in CSF of sCJD patients in comparison to control cases without prion disease." (PMID 27852982, 2016). "This very interesting finding encouraged us to study the MDH1 level in CSF of sCJD patients, in comparison to control cases without prion disease." (PMID 27852982, 2016). "Interestingly, we found levels of MDH1 reduced in brain tissue of sCJD patients compared to control brains (from patients without prion disease)." (PMID 27852982, 2016).
amyloid (2 papers, 2023 to 2024). "Furthermore, according to previously published data, protein levels of FABP3 and CAPG may increase in an age-dependent manner in microglia of amyloid mouse models, while the protein levels of MDH1 appear to decrease in the very same mice." (PMID 37775827, 2023). "BCAN, MDH1, PCOLCE and SELENBP1, to our knowledge, have not previously been implied in CAA/amyloid pathology." (PMID 38191511, 2024).
hepatocellular carcinoma (2 papers, 2025). A malignant tumor that arises from hepatocytes. "Moreover, in hepatocellular carcinoma and osteoblasts, CARM1 induces complex metabolic reprogramming by methylating targets including Malate Dehydrogenase 1 (MDH1), Glyceraldehyde-3-Phosphate Dehydrogenase (GAPDH), and Protein Phosphatase 1 Catalytic Subunit Alpha (PPP1CA)." (PMID 41488004, 2025).
mild cognitive impairment (2 papers, 2023 to 2025). "Endo-lysosomal proteins (e.g., HEXB, TPP1, SIAE) increased early in abundance alongside neurodegeneration-related proteins, and were followed by increases in metabolic proteins such as ALDOA, MDH1, and GOT1 at the mild cognitive impairment (MCI) stage." (PMID 40329321, 2025).
neuroblastoma (2 papers, 2021 to 2025). Neuroblastoma (NB) is the most common solid, extracranial childhood tumor. "MDH1 expression showed an inverse correlation with CTL activity in UCEC, metastatic melanoma, neuroblastoma, leukemia, and TNBC." (PMID 40948768, 2025). "A number of genes involved in mitochondrial function and responsive to PGC-1α overexpression in human neuroblastoma cells are reduced, including ATP5A1, glutamic-oxaloacetic transaminase 1 (GOT1;), IDH3A, and malate dehydrogenase 1 (MDH1;)." (PMID 33572179, 2021).
non-small cell lung carcinoma (2 papers, 2023 to 2025). A group of at least three distinct histological types of lung cancer, including non-small cell squamous cell carcinoma, adenocarcinoma, and large cell carcinoma. "MDH1 gene amplification was most commonly observed in non-small cell lung carcinoma (NSCLC), UCEC, BLCA, and ovarian cancers, while mutations were predominantly found in COAD." (PMID 40948768, 2025). "The levels of MDH1 and MDH2 enzymes in the cytoplasm and mitochondria of non-small-cell lung cancer (NSCLC) cells have been shown to be elevated compared with normal cells, and MDH1 enzyme activity was significantly higher than that of MDH2." (PMID 37151882, 2023).
Obesity (2 papers, 2020 to 2024). Accumulation of substantial excess body fat. "Previous studies in obesity reported that acetylation levels of MDH1 are significantly increased during adipocyte differentiation." (PMID 38703299, 2024).
Parkinson disease (2 papers, 2017 to 2024). A progressive degenerative disorder of the central nervous system characterized by loss of dopamine producing neurons in the substantia nigra and the presence of Lewy bodies in the substantia nigra and locus coeruleus. "Five to seven pQTL were observed for phosphoglycerate mutase 1 (PGAM1), the putative Parkinson disease autosomal recessive early onset 7 variant 1 (PARK7), triose phosphate isomerase (TPI1), peroxiredoxin 4 (PRDX4), malate dehydrogenase 1 (MDH1) and 3-hydroxyanthranilate 3,4-dioxygenase (HAAO)." (PMID 28424047, 2017).
Ataxia (1 paper, 2019). Ataxia refers to impaired coordination of voluntary muscle movement. "Online databases, such as MalaCards, have listed diseases associated with MDH1 to include tetanus neonatorum and x-linked sideroblastic anemia with ataxia." (PMID 31817761, 2019).
cognitive decline (1 paper, 2023). "Here, we found that MDH1 was significantly decreased in AD, and correlated with the typical pathologies of AD, and parallel with clinical cognitive decline." (PMID 37575300, 2023). "Pearson correlation analysis found that the IDH3G, DLD, SUCLA2, MDH1 showed moderate positive correlations with MMSE scores (r = 0.365–0.441, p < 0.05), suggesting that their expression can effectively track the progression of cognitive decline." (PMID 37575300, 2023).
colon carcinoma (1 paper, 2019). "We performed ChIPseq using HCT116 colon carcinoma cells, identifying ~850 putative target genes associated with metabolism (e.g., Prdx5, Mdh1, Ahcy), transcription (Taf12, Tet2, histones), malignancy (Met, Blcap, Rras, Jag1, Gsk3a) and mitotic stability (Zbtb4)." (PMID 31059499, 2019).
dementia (1 paper, 2023). Loss of intellectual abilities interfering with an individual's social and occupational functions. "Of note, the CSF levels of FABP3, MDH1, and GDI1 were not only significantly elevated in participants diagnosed with AD, but also in the non-dementia classed MCI group when compared to CNC." (PMID 37775827, 2023).
diabetes (1 paper, 2026). "For diabetes, citrate synthase (CS) and malate dehydrogenase 1 (MDH1) impaired glucose oxidation via the TCA cycle, while hexose-6-phosphate dehydrogenase (H6PD) disrupted gluconeogenesis." (PMID 41531306, 2026).
Duchenne muscular dystrophy (1 paper, 2024). Duchenne muscular dystrophy (DMD) is a neuromuscular disease characterized by rapidly progressive muscle weakness and wasting due to degeneration of skeletal, smooth and cardiac muscle. "A deficiency of malate dehydrogenase is linked to muscular system pathologies as reductions in both isoforms (MDH1 and MDH2) of malate dehydrogenase have been demonstrated in Duchenne muscular dystrophy." (PMID 39519852, 2024).
hearing loss (1 paper, 2022). "Other genes were related to BPD-associated outcomes such as retinopathy of prematurity (ROP, e.g., GBP3, FJX1, HIPK2) and hearing loss (e.g., GJB6, TMEM63B) and mitochondrial energy metabolism (e.g., TOMM7, SLC25A26, SLC25A33, PDK1, PKM, MDH1)." (PMID 35484630, 2022).
ischemia (1 paper, 2023). A hypoperfusion of the BLOOD through an organ or tissue caused by a PATHOLOGIC CONSTRICTION or obstruction of its BLOOD VESSELS, or an absence of BLOOD CIRCULATION. "Supplementation of Tat-MDH1 immediately after ischemia alleviated ischemia-induced hyperlocomotion and neuronal damage 1 and 4 days after ischemia." (PMID 37024665, 2023). "Transient increases in MDH1 immunoreactivity were detected in the hippocampal CA1 region 6–12 h after ischemia, but MDH1 activity significantly decreased 2 days after ischemia." (PMID 37024665, 2023). "Tat-MDH1 treatment alleviated ischemia-induced increases in locomotor activity 1 d after ischemia and neuronal damage 4 d after ischemia in a concentration-dependent manner." (PMID 37024665, 2023). "Tat-MDH1 treatment maintained the redox status of the glutathione system in the hippocampus 2 days after ischemia." (PMID 37024665, 2023). "MDH1 immunoreactive neurons were abundantly observed in the stratum pyramidale 6 h after ischemia and MDH1 immunoreactive dendrites were found in the stratum radiatum." (PMID 37024665, 2023). "In addition, we confirmed the delivery of 1 mg/kg Tat-MDH1 into the gerbil hippocampus 6 h after ischemia." (PMID 37024665, 2023). "In conclusion, Tat-MDH1 has a neuroprotective potential against H2O2-induced oxidative stress in HT22 cells and ischemia-induced ischemic damage in the gerbils." (PMID 37024665, 2023). "In this study, we examined the role of cytoplasmic MDH (MDH1) in hydrogen peroxide (H2O2)-induced oxidative stress in HT22 cells and ischemia-induced neuronal damage in the gerbil hippocampus." (PMID 37024665, 2023). "In the present study, we observed that MDH1 immunoreactivity transiently and significantly increased in the CA1 region 6–12 h after ischemia." (PMID 37024665, 2023). "In addition, treatment with Tat-MDH1 significantly ameliorated ischemia-induced hydroperoxide levels, MDA levels, and DHE fluorescence in the hippocampus 2 d after ischemia." (PMID 37024665, 2023). "From 4 to 7 d after ischemia, MDH1 immunoreactive neurons were found in the non-pyramidal cells of the CA1 region; however, their immunoreactivity was similar to those in the sham-operated group." (PMID 37024665, 2023).
leiomyoma (1 paper, 2016). A well-circumscribed benign smooth muscle neoplasm characterized by the presence of spindle cells with cigar-shaped nuclei, interlacing fascicles, and a whorled pattern. "In addition, PTRF co-expresses with KRT1, CCT5 co-expresses with MHI1; GOT1 co-expresses with MHI1; and MHI1 co-expresses with LDHB; indicating not only an interaction between LDHB, GOT1 and MDH1, but also a possible association between them and the leiomyoma." (PMID 27070597, 2016).
lung disease (1 paper, 2014). "Ramp2 [Receptor (calcitonin) activity modifying protein 2], Acaa2 (Acetyl-Coenzyme A acyltransferase 2), Mdh1 (Malate dehydrogenase 1, NAD), and Tspan8 (Tetraspanin 8) are enriched mRNAs in the lungs and are involved in lung disease." (PMID 25070658, 2014).
malignant glioma (1 paper, 2024). A grade III or grade IV glioma arising from the central nervous system. "Published data on the three potential prognostic biomarkers identified, FABP7, MDH1 and RNH1, indicate that high levels of FABP7 are associated with a poor prognosis for patients with various types of tumors, including malignant gliomas." (PMID 38803161, 2024).
metabolic syndrome (1 paper, 2023). A cluster of metabolic risk factors for CARDIOVASCULAR DISEASES and TYPE 2 DIABETES MELLITUS. "Our study showed that the expression levels of oxidoreductases, including d-3-phosphoglycerate dehydrogenase (PHGDH) and malate dehydrogenase (MDH1), were also decreased at the symptomatic stage of the metabolic syndrome, which may further worsen oxidative stress." (PMID 37107219, 2023).
osteosarcoma (1 paper, 2023). A usually aggressive malignant bone-forming mesenchymal neoplasm, predominantly affecting adolescents and young adults. "Mitochondrial dysfunction in osteosarcoma cells caused by a mtDNA mutation resulted in loss of malate-aspartate shuttle activity and re-oxidation of NADH by cytoplasmic malate dehydrogenase 1 (MDH1)." (PMID 36805760, 2023).
schwannoma (1 paper, 2024). A benign, usually encapsulated slow growing tumor composed of Schwann cells. "RNA sequencing showed IDH1/2 and MDH1/2, which produce α-ketoglutarate or succinic acid, respectively, were suppressed following schwannoma cell radiotherapy." (PMID 38216587, 2024).
sporadic Creutzfeldt-Jakob disease (1 paper, 2016). A rare sporadic human prion disease characterized by rapidly progressive cognitive impairment in combination with variable neurologic signs and symptoms including myoclonus, visual or cerebellar problems, pyramidal or extrapyramidal features, or akinetic mutism. "A previous two-dimensional proteomic study on cerebrospinal fluid (CSF) revealed an elevated level of an enzyme, mitochondrial malate dehydrogenase 1 (MDH1), in sporadic Creutzfeldt-Jakob disease (sCJD) patients." (PMID 27852982, 2016).
Stroke (1 paper, 2023). Sudden impairment of blood flow to a part of the brain due to occlusion or rupture of an artery to the brain. "Incidence and risk of stroke increases with age, whereas MDH1 is susceptible to alterations during aging." (PMID 37024665, 2023).
testicular germ cell tumor (1 paper, 2025). A germ cell tumor arising from the testis. "By comparing the differential methylation between cancerous and non-cancerous samples in the UALCAN database, we observed a correlation between higher MDH1 expression levels in LUAD, BLCA, thyroid carcinoma (THCA), and testicular germ cell tumors (TGCT) and reduced methylation levels." (PMID 40948768, 2025).
uveal melanoma (1 paper, 2025). A melanoma derived from melanocytes of the uveal tract. "Our result unraveled that MDH1 expression was an adverse factor for OS, DSS, and PFI in LUAD, Uveal Melanoma (UVM), and KICH." (PMID 40948768, 2025).
varicocele (1 paper, 2020). A condition characterized by the dilated tortuous veins of the spermatic cord with a marked left-sided predominance. "Nonetheless, proteins, such as CLGN, FTH1, MDH1, MIF, PPP3CA, SUCLA2, and PSMA7, involved in sperm function, apoptosis, and oxidative stress were present in a low and very low abundance in the unilateral and bilateral varicocele group, respectively." (PMID 32365753, 2020).
cancer (30 papers, 2012 to 2025). A tumor composed of atypical neoplastic, often pleomorphic cells that invade other tissues. "A significant association has been observed between MDH1 expression and various characteristics of the tumor microenvironment across different cancer types." (PMID 40948768, 2025). "MDH1 expression levels are elevated across a wide range of malignancies, and overexpression of MDH1 was consistently linked to poor prognosis in multiple cancer subtypes." (PMID 40948768, 2025). "In a comprehensive analysis of 19 immunotherapy cohorts and a pan-cancer single-cell immunotherapy dataset, a significant finding was the elevated expression of MDH1 in patients who were sensitive to immunotherapy." (PMID 40948768, 2025). "The complex interaction between MDH1 and macrophages in the tumor microenvironment, along with its impact on the efficacy of immunotherapies in various cancers, is particularly significant." (PMID 40948768, 2025). "To summarize, the research findings indicate a consistent elevation of MDH1 expression across a range of cancers, with a strong correlation to poor oncological outcomes." (PMID 40948768, 2025). "The scRNA-seq and functional enrichment analyses reveal that MDH1 is primarily expressed in macrophages and cancer cells, with a strong positive correlation to the proliferation and metastatic potential of LUAD." (PMID 40948768, 2025). "Drug sensitivity profiling and molecular docking techniques have been employed to identify potential anti-cancer compounds targeting MDH1." (PMID 40948768, 2025). "Excessive MDH1 activity has also been shown to increase proliferation in cancer and strengthen cellular resistance to metabolic stress." (PMID 41142618, 2025). "In cancer cells, depletion of MDH1 has been shown to slow down both proliferation rates and glucose uptake." (PMID 40948768, 2025). "In the subsequent phase of our study, we explored MDH1 mRNA expression in cancerous tissues involved in 33 cancer types, utilizing data from TCGA." (PMID 40948768, 2025). "MDH1 is amplified in a broad spectrum of cancers and this amplification is correlated with poor prognosis." (PMID 38803161, 2024). "MDH1 is frequently overexpressed in cancer cells, where it has been shown to enhance glycolysis by replenishing the cytosolic cofactor NAD+." (PMID 36837832, 2023). "Recently, AC1497 (methyl 3-(3-(4-(2,4,4-trimethylpentan-2-yl)phenoxy)propanamido)benzoate) was developed as a dual inhibitor of MDH1/2 targeting cancer metabolism." (PMID 34452103, 2021). "Our findings indicate that MDH1 may serve as a potential prognostic marker and a promising target for cancer immunotherapy." (PMID 40948768, 2025). "In cancer: Expression and activity of MDH1 are frequently elevated." (PMID 41142618, 2025). "Considering its essential metabolic roles and its reported involvement in various cancers, MDH1 may be an important player in a wide range of tumor types and tumorigenic processes." (PMID 40948768, 2025). "Furthermore, single-cell RNA sequencing data from TISCH and HPA confirmed the presence of MDH1 transcripts in both macrophages and malignant tumor cells across most of the cancer types studied." (PMID 40948768, 2025). "In addition, synthetic-lethal combinations (e.g., pairing MDH1 blockade with oxidative-stress inducers) warrant pre-clinical evaluation to exploit metabolic vulnerabilities unique to cancer cells while sparing normal tissues." (PMID 40948768, 2025). "Overall, these findings suggest that AS events in MDH1 may take a significant role in the progression of various cancers." (PMID 40948768, 2025). "Therefore, there is a critical need to examine the expression patterns of MDH1 across different cancer types, which is essential for guiding future experimental and clinical research." (PMID 40948768, 2025). "In conclusion, the conducted analyses suggest that MDH1 may serve as a prospective prognostic biomarker for a range of cancers, with particular relevance to LUAD." (PMID 40948768, 2025).